ALOX5 (arachidonate 5-lipoxygenase)
Diseases named in the same sentence as ALOX5 in open-access papers (continued):
Sharing a sentence is not in itself a finding about the gene and the disease.
atherosclerosis (continued). "Our results provided novel targets for predicting atherosclerotic plaque progression and confirmed that ALOX5 and NCF2 have good diagnostic value for atherosclerosis." (PMID 36035208, 2022). "The involvement of ALOX5 in atherosclerosis is not only during the development of atherosclerotic plaques but also during the progression of atherosclerotic plaques toward instability." (PMID 27781209, 2016). "Dwyer et al8 reported that the observed association between ALOX5 SP1 tandem variation and atherosclerosis was modified by dietary intakes of AA, EPA, and DHA." (PMID 27025886, 2016). "In contrast to these results, subsequent studies have been unable to demonstrate a relationship between ALOX5 SNPs and atherosclerosis or CHD." (PMID 27025886, 2016). "Polymorphisms within ALOX12, ALOX5, and ALOX5AP are genetically associated with subclinical atherosclerosis and with biomarkers of disease in families with type 2 diabetes." (PMID 20592751, 2010). "The ALOX12, ALOX15, ALOX5, and ALOX5AP genes represent strong candidates for atherosclerosis risk, especially in the context of type 2 diabetes." (PMID 20592751, 2010). "An association between changes away from the common allele (5 repeats) in a repeat-polymorphism (ALOX5P) comprised of Sp1 binding sites in the promoter region of ALOX5 and atherosclerosis has been previously reported." (PMID 18248681, 2008). "In conclusion, we identified the targets of ferroptosis in atherosclerosis associated with garlic, including GPX4, DPP4 and ALOX5, providing new mechanistic insights that may be clinically relevant for combination therapies of garlic." (PMID 39108744, 2024). "Thus, in a mouse model, it was demonstrated that the knock out of the ALOX-5 gene led to a high resistance against the development of atherosclerosis." (PMID 27893808, 2016). "In addition, high levels of ALOX-5 and LTA4-H in human plaques have been associated with symptoms of plaque instability, suggesting a key role of the 5-LOX pathway in late stages of atherosclerosis and atherothrombotic events." (PMID 27893808, 2016). "ALOX5 gene variants do not appear to be related to clinical CHD events or subclinical atherosclerosis regardless of bioavailable enzyme substrate levels in this multiethnic cohort." (PMID 27025886, 2016). "Thus ALOX5 is believed to potentially accelerate atherosclerosis by promoting the inflammatory process within the arterial wall through increased synthesis of LTs by leukocytes." (PMID 25444678, 2014). "We hypothesize that polymorphisms in ALOX12, ALOX15, ALOX5, and ALOX5AP genes are associated with subclinical atherosclerosis in multiple vascular beds." (PMID 20592751, 2010). "Whilst deviation away from the common 5-allele of the ALOX5 promoter microsatellite (ALOX5P) has been previously associated with an increased risk of atherosclerosis, allelic variation at the three ALOX5 coding SNPs (g.20C>T; g.8322G>A; g.50778G>A) has not." (PMID 18248681, 2008). "Recent studies have discovered that Jak2V617F, ALOX5, and NCF2 are involved in the formation of atherosclerosis by regulating macrophage ferroptosis." (PMID 36290297, 2022). "ALOX5 has been seen to be up-regulated in Down Syndrome, severe combined immunodeficiency (SCID), among others, and down-regulated in atherosclerosis." (PMID 33546175, 2021). "In the large multiethnic study, the links between none of 1348 ALOX5 (arachidonate 5-lipoxygenase, 5-LOX) polymorphisms and subclinical atherosclerosis, as well as CAD events, were found." (PMID 36009459, 2022). "The mouse 5-LO gene, ALOX5, has been shown to contribute to the development of atherosclerosis." (PMID 20592751, 2010). "In addition, they demonstrated that CB-ECFCs were able to decrease the expression of mediators of inflammation and atherosclerosis produced by allogeneic lymphocytes and monocytes (IL-1β, IL-8, PGF, ALOX-5, TNFα, CSF-2, MMP-1, MMP-9) more significantly than adult ECFCs." (PMID 32381102, 2020).
breast carcinoma (41 papers, 2007 to 2025). "ALOX5 has been implicated in the pathophysiological process of breast cancer and is associated with increased breast cancer risk." (PMID 38140764, 2024). "Furthermore, ALOX5 expression was reduced in tumour‐associated macrophages (TAMs) generated by co‐culturing human macrophages with MCF‐7 breast cancer cells, resulting in cell death." (PMID 38140764, 2024). "Among the 8-gene signature of high immune cell infiltration (type C2), ALOX5 has been found to promote gastric cancer growth and attenuate chemotherapy toxicity, while in breast cancer, ALOX5 activation is associated with HER2 expression as well as mediates breast cancer growth and migration." (PMID 35962453, 2022). "Wculek & Malanchi showed that neutrophils are involved in lung metastasis in mouse breast cancer models, whereas drug- or gene-mediated suppression of the leukotriene-generating enzyme arachidonate 5-lipoxygenase abolished neutrophil-associated pro-metastatic functions." (PMID 33363026, 2020). "Since high-levels of arachidonic acid are associated with promoting cancer cell proliferation in breast cancer tissues, we speculated that inhibition by Nordy may also be involved in regulating the Alox-5 pathway." (PMID 24454929, 2014). "In fact, serum ALOX5 levels were found to be nearly twofold higher in breast cancer patients compared to controls." (PMID 38140764, 2024). "Significant differences were observed in breast cancer tumour staging for ALOX5, ALOXE3, ALOX12, and ATF3 genes." (PMID 38516826, 2024). "Genetic or pharmacological inhibition of ALOX5 also eliminates the pro‐metastatic activity of neutrophils, thereby reducing breast cancer metastasis." (PMID 38140764, 2024). "The last target gene, ALOX5, was reported to play a role in colon cancer, breast cancer, and lung cancer." (PMID 35401884, 2022). "For example, researchers investigated the expression and functions of ALOX5 in breast cancer cells, and demonstrated that inhibiting ALOX5 had therapeutic potential in breast cancer." (PMID 34983358, 2022). "In particular, ALOX5 plays a presumptive role in the breast cancer progression and patient prognosis." (PMID 36551179, 2022). "By targeting Alox5 with zileuton (an Alox5 inhibitor), the spontaneous metastatic rate and the seeding capacity of cancer cells into the lungs were greatly reduced in a metastatic breast cancer mouse model." (PMID 34202411, 2021). "In White women, an increased risk of ER+ breast cancer was observed for COX2-rs689470 (OR: 2.60, 95% CI: 1.46–4.63) in the dominant model, whereas a reduced risk was observed for ALOX5-rs7099874 (OR: 0.66, 95% CI: 0.51–0.85) in a dominant model." (PMID 34249719, 2021). "The ALOX5-rs7099874 and ALOX5AP-rs9579648 were specifically associated risk of ER+ breast cancer, while ALOX5AP-rs9315048 were associated with risk of ER− cancer, in either White or Black women." (PMID 34249719, 2021). "A number of these SNPs in COX2, ALOX5, ALOX5AP, and ALOX12 genes were found to be associated with overall breast cancer risk, as well as breast cancer risk in subgroups defined by menopausal and ER status, in either White or Black women." (PMID 34249719, 2021). "In this study, we identified several SNPs in the ALOX5 and ALOX5AP genes that showed associations with overall breast cancer risk and differences by menopausal and ER status, in either White or Black women." (PMID 34249719, 2021). "We found that the ALOX5 expression and activity were upregulated in breast cancer patients, particularly in those tissues with HER2-positive." (PMID 33224971, 2020). "In contrast, HER2 inhibition led to decreased expression and activity of ALOX5 but not ALOX5AP, suggesting that HER2 specifically regulates the ALOX5 expression and activity in breast cancer cells." (PMID 33224971, 2020). "Our findings also highlight the therapeutic value of inhibiting ALOX5 in breast cancer, particularly those patients with the HER2 overexpression." (PMID 33224971, 2020).
breast carcinoma (continued). "We further demonstrated that ALOX5 is important for breast cancer biological activities with the predominant roles in growth and migration, likely through RhoA, focal adhesion, and PI3K/Akt/mTOR signaling but not epithelial mesenchymal transition (EMT)." (PMID 33224971, 2020). "Notably, inhibiting the leukotriene-producing enzyme arachidonate 5-lipoxygenase (Alox5) through genetic or pharmacological interventions can abolish the pro-metastatic activity of neutrophils, thereby reducing the transfer of breast cancer cells to the lungs." (PMID 40342932, 2025). "In breast cancer, ALOX5 expression within neutrophils reportedly promotes metastasis to the lungs." (PMID 38090559, 2023). "It was also found that ALOX5 is positively correlated with tumor stage of breast cancer which could accelerate the growth of breast cancer cells." (PMID 36467032, 2022). "In White women, an increased risk of breast cancer was observed for COX2-rs689470 (OR: 2.02, 95% CI: 1.16–3.53) in the dominant model and ALOX5-rs1487562 (OR: 1.80, 95% CI: 1.02–3.18) in the recessive model, while the association among Black women was essentially null." (PMID 34249719, 2021). "The results showed ALOX5 and DDP4 had the strongest positive correlation (r = 0.53), implying they were synergetic contributors to the genetic architecture of ferroptosis, and resulted in the susceptibility of breast cancer." (PMID 35154262, 2021). "Serum ALOX5 is elevated in breast cancer patients and can serve as a progressive protein marker." (PMID 34121352, 2021). "ALOX5 upregulation was also observed in HER2-positive breast cancer cells." (PMID 33224971, 2020). "Another study found that ALOX5 activation was correlated with HER2 expression and mediated breast cancer growth and migration, indicating the need for further investigation into the relationship between ALOX5 and HER2." (PMID 38140764, 2024). "In breast cancer, SBFI26, an inhibitor of FABP5, induces ferroptosis by elevating levels of ferrous ions and lipid peroxidation, increasing the expression of ALOXE3, ALOX5, and ALOX15, thus driving ferroptosis in tumor cells." (PMID 39633985, 2024). "In a previous report, we examined the genetic expression of COX1, COX2, ALOX5 and ALOX5AP in breast cancer specimens from TCGA." (PMID 37190308, 2023). "For example, the mRNA signatures ETFDH, EGF, PRKAB1, ALOX5, DHRS9, MTHFR, and MGHH are in the maximum interaction network and are connected to other breast-cancer-related, frequently altered genes." (PMID 36551179, 2022). "In this study, we demonstrate that the ALOX5 activation correlates with the HER2 expression and mediates breast cancer growth and migration." (PMID 33224971, 2020). "Our work is the first to report a correlation between the ALOX5 activity and HER2 overexpression in breast cancer." (PMID 33224971, 2020). "The results revealed that breast cancer tissues exhibited lower expression levels of SAT1, ALOX5, ALOX12, ATF3, ATF4, GPX4 and NFE2L2 compared to normal tissues; conversely, higher expression levels of ALOX15, ALOXE3 and HO‐1 were observed in breast cancer tissues than in normal tissues." (PMID 38516826, 2024). "The aberrant activation of ALOX5 is important for the proliferation and migration of breast cancer cells, whereas the absence of ALOX5 promotes the progression of bladder cancer by enabling the evasion of ferroptosis." (PMID 39090114, 2024). "A recent study has demonstrated that in the MMTV-PyMT breast cancer model, neutrophils express high levels of the lipids leukotriene B4 (LTB4) and cysteinyl leukotrienes C4, D4 and E4 (LTC/D/E4), products of the arachidonate 5-lipoxygenase (Alox5) enzyme." (PMID 27618112, 2016).
colon carcinoma (39 papers, 2012 to 2025). "We also found increased Alox5 expression in GM:F344 tumors, which is associated with increased proliferation and invasion of colonic tumors." (PMID 37458451, 2023). "Further biochemical experiments suggested that the rs702365 variant may regulate ALOX5 expression via a long-range regulatory mechanism and influence the proliferation of colon cancer cells." (PMID 37144561, 2023). "Abnormal expression of ALOX5 has been observed in various human cancers, including pancreas, prostate, and colon cancers." (PMID 39457550, 2024). "ALOX5 is upregulated in colon cancer, and its inhibition suppresses CRC progression through the PI3K/AKT pathway." (PMID 37144561, 2023). "ADIPOQ, ALOX5, and ALOX15 are reportedly associated with lung cancer, colorectal cancer, and colon cancer." (PMID 30071629, 2018). "Since such studies are not always possible in an in vivo situation and humans, we have resorted to the present study to know the metabolism of PUFAs and the expression of mPGES, COX-2 and ALOX5 are altered in colon cancer cells." (PMID 25886460, 2015). "We demonstrated, for the first time, that rs702365 [G] > [C] represses ALOX5 transcription and corollary experiments suggested that ALOX5 may promote colon cancer cell growth by mediating an inflammatory response." (PMID 37144561, 2023). "Elevated ALOX5 expression has been observed in colon cancer and esophageal adenocarcinoma." (PMID 34121352, 2021). "Melstrom et.al demonstrated that ALOX5 is overexpressed in colon cancer, and inhibition of ALOX5 could inhibit tumor growth in colon cancer xenograft model." (PMID 31528237, 2019). "Moreover, preliminary in vitro experiments suggested that reduced ALOX5 expression decreased the proliferative ability of colon cancer cells by inhibiting an inflammatory response, ultimately suppressing the development of colon cancer, which should be thoroughly tested by more functional assays." (PMID 37144561, 2023). "In the colon cancer cell lines HCT116 and SW480 treated with solanine, the expression of arachidonate 12-lipoxygenase B (ALOX12B) and arachidonate 5-lipoxygenase (ALOX5) was significantly upregulated in a dose-dependent manner." (PMID 41471274, 2025). "We verified that finding in colon cancer cell lines and found that lipid peroxide and the cell death percentage were reduced in HCT8 and HCT116 cells treated with CT/RT after ALOX5 knockdown by siRNAs." (PMID 37144561, 2023). "Rutin targets two proteins, namely NT5E and EGFR, which both interact with established colon cancer drug targets and two proteins that are part of the colon cancer prognostic signature gene set (CYP1B1 and ALOX5)." (PMID 24886433, 2014). "In LoVo and RKO colon cancer cells, PUFAs can reduce the synthesis of PGE2 and LTB4, inhibit the expression of ALOX5, LTB4, mPGES, COX-2, and PGE2, and increase the expression of LXA4, thereby promoting apoptosis and inhibiting the growth of LoVo and RKO colon cancer cells." (PMID 36059851, 2022).
pancreatic cancer (33 papers, 2006 to 2025). "Of note, it has been reported that MGST1 directly interplayed with ALOX5 to cause ferroptosis inhibition via decreasing lipid peroxide production in pancreatic cancer cells." (PMID 39850123, 2025). "Upregulation of ALOX5 is implicated in all grades of human pancreatic intraepithelial lesions, and initial development of pancreatic cancer in EL-KRAS mice and N-nitroso-bis(2-oxopropyl) amine-treated hamsters." (PMID 38612771, 2024). "Lack of migrated natural killer T cells facilitates development of pancreatic cancer and their presence modulate tumor associated macrophages (M2) through ALOX5 and mPGES-1." (PMID 38612771, 2024). "Moreover, overexpression of ALOX5 in pancreatic cancer tissues has been associated with lymph node metastasis and TNM stage." (PMID 38612771, 2024). "Research on pancreatic cancer has demonstrated that ALOX5 can induce an M2-like phenotype in macrophages via the JAK/STAT pathway, thereby enhancing their chemotactic migration towards PANC-1 cells." (PMID 41030501, 2025). "Zileuton, an arachidonate 5-lipoxygenase (ALOX5) inhibitor, is able to reduce the invasiveness and metastasis of pancreatic cancer, where increased ALOX5 activity has been observed." (PMID 40872573, 2025). "Similar studies have demonstrated the use of both ALOX12 and ALOX5 inhibitors in pancreatic cancer cells PANC-1 and Capan2, which were shown to express ALOX5 and ALOX12." (PMID 38612771, 2024). "The invasive and metastatic role of ALOX5 in the progression of pancreatic cancer have been demonstrated both in vitro and in vivo using an approved ALOX5 inhibitor, Zileuton." (PMID 38612771, 2024). "Leukotriene B4—a downstream product of ALOX5—provokes growth of pancreatic tumors through activation of its receptors (BLT1/2), which are as well overexpressed in pancreatic tumor tissues." (PMID 38612771, 2024). "Findings from other research works show that overexpression of ALOX15 in pancreatic cancer cells and inhibition of ALOX5 and platelet-type 12-lipoxygenase exert anti-tumorigenic effects." (PMID 38612771, 2024). "For example, Nrf2-dependent microsomal glutathione S-transferase (MGST) expression was induced in CYP2E1-overexpressing HepG2 cells, and contributed to ferroptosis resistance in pancreatic cancer cells by inhibiting ALOX5 activity." (PMID 36993697, 2023). "Recent studies have reported that MGST1 can downregulate lipid peroxide production by binding ALOX5 during ferroptosis induction and ultimately inhibit ferroptotic cancer cell death, which is also regarded as a novel therapeutic target in pancreatic cancer." (PMID 35218676, 2022). "ALOX5 inhibition limited lipid peroxidation during ferroptosis and indirectly promoted the growth of pancreatic cancer cells." (PMID 34447410, 2021). "Additionally, multi-omics approaches combining weighted gene co-expression networks (WGCNA) with experimental validation identified biomarkers like ALOX5 (associated with invasion) and ADH1A (linked to chemosensitivity) in pancreatic cancer." (PMID 40422244, 2025). "In pancreatic cancer, ALOX5 is highly expressed, primarily in macrophages." (PMID 40034694, 2025). "However, another study reported that MGST1 inhibited ALOX5 expression via a direct interaction, which restrained ferroptosis in pancreatic cancer cells." (PMID 39850123, 2025). "In addition, MGST1 limits lipid peroxidation via interaction with ALOX5, resulting in inhibition of ferroptotic pancreatic cancer cell death." (PMID 38388563, 2024). "In vitro and in vivo experiments respectively in MiaPaCa-2, AsPC-1 human pancreatic cancer cell lines, and athymic mice xenograft models, show that inhibitors of ALOX5 (Rev-5901) and ALOX12 (baicalein) induce growth inhibition while activating apoptosis via the mitochondrial pathway." (PMID 38612771, 2024). "Kuang found that high expression levels of MGST1 in pancreatic cancer cells might bind to ALOX5, further reducing lipid peroxidation." (PMID 39160643, 2024).
pancreatic cancer (continued). "ALOX5 upregulates the expression of vimentin and downregulates the expression of E-cadherin to promote EMT in pancreatic cancer." (PMID 40034694, 2025). "In pancreatic cancer, MGST1 binds ALOX5 to inhibit lipid peroxide production during ferroptosis induction." (PMID 39711549, 2024). "Inhibition of ALOX5 by low-dose Zileuton led to the inhibition of invasion and metastasis in PANC-1 pancreatic cancer cells, and mitigated the M2-like phenotype through the JAK/STAT pathway in macrophages." (PMID 38612771, 2024). "To clarify the functional role of signature genes in PAAD cells, we used Cancer Cell Line Encyclopedia (CCLE) database to analyze the expression of ALOX5, ALOX12 and CISD1 in pancreatic cancer cells, and found that the expression of ALOX5 was relatively highly expressed in T3M4 cells." (PMID 35033072, 2022). "The results obtained with qPCR and IHC assays showed that ALOX5 was highly expressed regardless of whether ALOX12 and CISD1 were expressed at low levels in these pancreatic cancer tissue samples." (PMID 35033072, 2022).